NCAPD2 (non-SMC condensin I complex subunit D2)
Description:
Regulatory subunit of the condensin complex, a complex required for conversion of interphase chromatin into mitotic-like condense chromosomes. The condensin complex probably introduces positive supercoils into relaxed DNA in the presence of type I topoisomerases and converts nicked DNA into positive knotted forms in the presence of type II topoisomerases. May target the condensin complex to DNA via its C-terminal domain. May promote the resolution of double-strand DNA catenanes (intertwines) between sister chromatids. Condensin-mediated compaction likely increases tension in catenated sister chromatids, providing directionality for type II topoisomerase-mediated strand exchanges toward chromatid decatenation. Required for decatenation of non-centromeric ultrafine DNA bridges during anaphase. Early in neurogenesis, may play an essential role to ensure accurate mitotic chromosome condensation in neuron stem cells, ultimately affecting neuron pool and cortex size.
Synonyms: hCAP-D2; CNAP1; KIAA0159; CAP-D2; MCPH21
Tractability: PROTAC: ubiquitination databases record sites on it; its protein half-life has been measured.
Gene: Protein-coding gene on chromosome 12 (6,493,356 to 6,531,970, forward strand). Ensembl gene ENSG00000010292.
Subcellular location: Nucleus; Cytoplasm; Chromosome
Subcellular location (Human Protein Atlas): Cytosol; Nucleoplasm; Basal body; Centriolar satellite; Nucleoli; Primary cilium
Pathways (Reactome):
Cell Cycle: Condensation of Prometaphase Chromosomes
Gene Ontology:
Molecular function: histone binding; protein binding
Biological process: mitotic chromosome condensation; positive regulation of chromosome condensation; chromosome condensation; mitotic cell cycle
Cellular component: condensed chromosome; condensin complex; cytoplasm; cytosol; membrane; nuclear chromosome; nucleolus; nucleoplasm; condensed chromosome, centromeric region; nucleus; chromosome
Genetic constraint (gnomAD): Loss-of-function variants: 100 observed, 171.76 expected, observed/expected ratio (o/e) 0.58, 90% interval 0.49 to 0.69. The upper end of that interval is the gene's LOEUF score, 0.69, which puts it in group 2 of 6, group 1 being the genes least tolerant of losing a copy. Missense variants: 1,560 observed, 1,835.2 expected, observed/expected ratio (o/e) 0.85, 90% interval 0.81 to 0.89. Synonymous variants: 585 observed, 679.41 expected, observed/expected ratio (o/e) 0.86, 90% interval 0.8 to 0.92.
Homologues: Orthologues: chimpanzee NCAPD2 (99% identical), macaque NCAPD2 (95% identical), dog NCAPD2 (90% identical), pig NCAPD2 (90% identical), rabbit NCAPD2 (90% identical), rat Ncapd2 (86% identical), mouse Ncapd2 (86% identical), guinea pig NCAPD2 (84% identical), tropical clawed frog ncapd2 (60% identical), zebrafish ncapd2 (49% identical), Drosophila melanogaster Cap-D2 (28% identical). Paralogues in human: NCAPD3 (16% identical).
Diseases named in the same sentence as NCAPD2 in open-access papers:
NCAPD2 is named in the same sentence as 51 diseases in open-access papers, as found by Europe PMC text mining. Sharing a sentence is not in itself a finding about the gene and the disease. The quoted sentences say what the papers report.
breast carcinoma (10 papers, 2017 to 2024). "Furthermore, NCAPD2 is overexpressed in breast cancer and has been implicated in breast cancer prognosis." (PMID 37498296, 2023). "In-depth investigations into the mechanisms of NCAPD2 promoting cancer have been conducted in breast cancer and colorectal cancer." (PMID 39220139, 2024). "For example, NCAPD2 is overexpressed in breast cancer and promotes its development through transcriptional activation of CDK1." (PMID 39220139, 2024). "A study investigating 179 breast cancer samples revealed for the first time a connection between NCAPD2 and TNBC." (PMID 38473804, 2024). "According to the HPA database, NCAPD2 protein expression in colon cancer, breast cancer, lung adenocarcinoma, and lung squamous cell carcinoma was higher than that in the corresponding normal tissues." (PMID 37498296, 2023). "NCAPD2 knockdown inhibits breast cancer progression by inhibiting proliferation, migration, and apoptosis in vitro and in vivo." (PMID 37498296, 2023). "TUBA1B, SLC2A1, PGK1, CCND1, and NCAPD2 have been overexpressed in breast cancer tissues and their promoter region was hypomethylated (The graph on top shows gene expression and the graph at the bottom shows methylation beta value)." (PMID 35622738, 2022). "Also, breast cancer cells transfected with siRNA for NCAPD2 inhibited its expression and consequently inhibited the proliferation and invasion of cancer cells." (PMID 35622738, 2022). "Previously, studies have found that NCAPD2 could promote breast cancer progression." (PMID 37192046, 2023). "Previous research has demonstrated that poor prognosis is correlated to abnormal condensin complex I expression of the NCAPH, NCAPG, and NCAPD2 subunits in NSCLC, liver cancer, colorectal cancer, breast cancer, and prostate cancer." (PMID 38566039, 2024). "In this study, for the first time, we report five oncogenes (TUBA1B, SLC2A1, PGK1, CCND1, and NCAPD2) and two tumor suppressors’ genes (RPLP2, RPL37) as novel therapeutic targets in breast cancer." (PMID 35622738, 2022). "For the first time in this study, we used a comprehensive in silico approach and identified five proto-oncogenes (TUBA1B, SLC2A1, PGK1, CCND1, and NCAPD2) and two tumor suppressor genes (RPLP2, RPL37) as novel therapeutic targets against breast cancer." (PMID 35622738, 2022). "On the other hand, NCAPD2 could affect tumor cell proliferation, apoptosis, migration and invasion by targeting CDK1 in breast cancer." (PMID 35927248, 2022). "Ncapd2 (non-SMC condensing I complex subunit D2) is involved in mitotic sister chromosome segregation without notable involvement in breast cancer." (PMID 28212608, 2017).
colorectal cancer (6 papers, 2023 to 2025). A primary or metastatic malignant neoplasm that affects the colon or rectum. "Previous studies report that NCAPD2 plays an essential role in colorectal tumorigenesis and the progression of colorectal cancer." (PMID 39917394, 2025). "In an AOM/DSS-induced mouse model, suppression of the development of colorectal cancer by NCAPD2 deletion is seen." (PMID 39403142, 2024). "NCAPD2 is similarly upregulated in colorectal cancer and NCAPD2 inhibits autophagy and promotes CRC cell proliferation and migration through the Ca2+/CAMKK/AMPK/mTORC1 pathway and PARP-1/SIRT1 axis." (PMID 37498296, 2023). "NCAPD2 plays a role in colorectal cancer through Ca2+/CAMKK/AMPK/mTORC1 pathway and PARP-1/SIRT1 axis and can be used as a potential therapeutic target." (PMID 37192046, 2023). "Additionally, NCAPD2 has been shown to hinder autophagy, thereby facilitating the progression of colorectal cancer." (PMID 39220139, 2024).
lung adenocarcinoma (5 papers, 2023 to 2025). A carcinoma that arises from the lung and is characterized by the presence of malignant glandular epithelial cells. "The impact of NCAPD2 on the invasive and metastatic capabilities of lung adenocarcinoma (LUAD) cells in vivo were investigated through a tail vein injection model." (PMID 41319185, 2025). "Subsequently, the immune infiltration level and immune subtype of NCAPD2 in lung adenocarcinoma (LUAD) and lung squamous cell carcinoma (LUSC) were analyzed using TIMER1 and TISIDB." (PMID 38172945, 2024). "The pro-oncogenic effects of NCAPD2 have been extensively studied across various tumor types; however, its precise role within the context of lung adenocarcinoma (LUAD) remains elusive." (PMID 39220139, 2024). "However, the role of NCAPD2 in lung adenocarcinoma (LUAD) remains largely unexplored." (PMID 41319185, 2025).
gastric cancer (4 papers, 2020 to 2024). A primary or metastatic malignant neoplasm involving the stomach. "hsa_circ_0005699 was previously reported to downregulate MCM8 and NCAPD2 expression by acting as a sponge of hsa-miR-504, functioning as tumor suppressor in gastric cancer." (PMID 33553144, 2020). "NCAPD2 showed good predictive ability (AUC > 0.7) in HNSC and melanoma, MSI showed good predictive ability (AUC > 0.7) in melanoma and gastric cancer, and TMB had good predictive ability (AUC > 0.7) in urothelial cancer." (PMID 37498296, 2023).
lung carcinoma (4 papers, 2023 to 2025). "Further preclinical and clinical studies are warranted to test the efficacy and safety of NCAPD2-targeted strategies in lung cancer management." (PMID 41319185, 2025). "The results revealed a significant reduction in the metastasis of lung cancer cells upon NCAPD2 knockdown, evidenced by a marked decrease in the total photon count in lung tumors." (PMID 41319185, 2025). "Further studies are needed to identify the detailed mechanism by which NCAPD2 modulates lung cancer." (PMID 39927632, 2025). "In addition, nanoparticle-based siRNA delivery systems have shown efficacy in preclinical lung cancer models, providing another potential route for NCAPD2 inhibition." (PMID 41319185, 2025). "The influence of NCAPD2 on the lung cancer is mediated by its capacity to regulate the cell cycle." (PMID 39927632, 2025). "These researches might be useful to detect the role of NCAPD2 for immunotherapy in pan-cancer especially lung cancer." (PMID 38172945, 2024). "Moreover, using the HPA database, it was found that NCAPD2 expression was higher in colon, breast, and lung cancers than in normal tissues." (PMID 37498296, 2023). "In order to further understand the impact of NCAPD2 on LUAD progression, we performed IHC analysis on both human lung cancer tissues and BALB/c nude mouse model of lung metastasis." (PMID 41319185, 2025).
triple-negative breast carcinoma (4 papers, 2020 to 2024). An invasive breast carcinoma which is negative for expression of estrogen receptor (ER), progesterone receptor (PR), and human epidermal growth factor receptor 2 (HER2). "The abnormal expression of NCAPD2 in triple-negative breast cancer has the potential to function as an independent prognostic factor." (PMID 39403142, 2024). "Further, knocking down NCAPD2, a subunit of condensin I, has led to apoptosis in triple-negative breast cancer cells." (PMID 32070024, 2020). "We could find only one study that reported that a higher NCAPD2 protein expression was significantly correlated with poor overall survival and worse disease-free survival in triple-negative breast cancer." (PMID 35622738, 2022).
Alzheimer disease (3 papers, 2017 to 2024). A progressive, neurodegenerative disease characterized by loss of function and death of nerve cells in several areas of the brain leading to loss of cognitive function such as memory and language. "Some reports have found that NCAPD2 is linked to several neurodegenerative diseases, such as Alzheimer’s disease and Parkinson’s disease, indicating the effect of NCAPD2 in the development of the central nervous system." (PMID 37498296, 2023). "In addition, a number of studies have demonstrated that NCAPD2 is linked to a number of neurodevelopmental diseases, including Alzheimer’s disease, autism, Parkinson’s disease, and others, which suggests that it may have a function in the development of the central nervous system." (PMID 39403142, 2024).
liver cancer (3 papers, 2023 to 2024). An epithelial or non-epithelial malignant neoplasm that arises from the liver. "We performed immunohistochemistry (IHC) on liver cancer and corresponding normal tissues to examine NCAPD2 protein expression in LIHC." (PMID 37498296, 2023). "We selected liver cancer for the IHC study and we found that NCAPD2 was up-regulated in LIHC and NCAPD2 expression was related to T stage, pathologic stage, and histologic grade." (PMID 37498296, 2023).
microcephaly (3 papers, 2019 to 2024). A congenital or acquired developmental disorder in which the circumference of the head is smaller than normal for the person's age and sex. "For example, biallelic mutations in NCAPD2, NCAPH, and NCAPD3 cause microcephaly." (PMID 36169232, 2022).
ovarian carcinoma (3 papers, 2015 to 2023). A malignant neoplasm originating from the surface ovarian epithelium. "NCAPD2 is also upregulated in ovarian cancer, wherein amplification and mutations have been observed." (PMID 37498296, 2023). "The NCAPD2 is a novel candidate genes in ovarian cancer (Tatsumoto & T, 1999; Fields & Justilien, 2009)." (PMID 33552715, 2021).
Parkinson disease (3 papers, 2017 to 2024). A progressive degenerative disorder of the central nervous system characterized by loss of dopamine producing neurons in the substantia nigra and the presence of Lewy bodies in the substantia nigra and locus coeruleus. "The NCAPD2 gene is positively correlated with the risk of Parkinson’s disease in the Han population and acts as a latent genetic marker for sporadic Parkinson’s." (PMID 37498296, 2023).
lymph node metastasis (2 papers, 2023). "NCAPD2 was overexpressed in LUAD patients with lymph node metastasis (N+)." (PMID 36701707, 2023). "The expression of NCAPD2 in cancer with lymph node metastasis was significantly higher than that without lymph node metastasis in CHOL, KICH, KIRC, KIRP, and LUAD and significantly lower in SKCM." (PMID 37498296, 2023).
melanoma (2 papers, 2023 to 2024). A malignant, usually aggressive tumor composed of atypical, neoplastic melanocytes. "In the melanoma cohort, NCAPD2 with high expression was associated with a better prognosis after anti-PD-1 therapy." (PMID 37498296, 2023). "Moreover, in the melanoma cohort, highly expressed NCAPD2 was associated with a better prognosis after treatment with PD-1 inhibitors." (PMID 37498296, 2023).
Primary microcephaly (2 papers, 2022 to 2024). Head circumference below 2 standard deviations below the mean for age and gender at birth. "Studies have also revealed that a novel homozygous splice site variant in the NCAPD2 gene caused primary microcephaly." (PMID 38172945, 2024). "In addition, also mutations in genes encoding condensin I and II complex members are associated with primary microcephaly, e.g., NCAPD2, NCAPH, NCAPG2 or NCAPD3, which showed altered expression levels in our data as well." (PMID 35099000, 2022).
sarcoma (2 papers, 2023). A usually aggressive malignant neoplasm of the soft tissue or bone. "Our research confirmed the value of high expression of NCAPD2 in the prognosis of human sarcoma by using the Kaplan-Meier plotter and GEPIA database, and found that it was negatively correlated with the OS and DFS of sarcoma patients." (PMID 37192046, 2023). "By evaluating NCAPs in normal and sarcoma tissues using the GEPIA database, we noticed significantly higher expression patterns of NCAPD2, NCAPG, NCAPH, NCAPG2, and in sarcoma samples compared to normal tissues." (PMID 37192046, 2023). "Six members of the NCAPs family, including NCAPD2, NCAPG, NCAPH, NCAPD3, NCAPG2, and NCAPH2, have been found in different types of sarcomas." (PMID 37192046, 2023). "GEPIA database showed that high expression of NCAPD2, NCAPH, NCAPG and NCAPG2 had a significant correlation with poor overall survival of sarcoma patients (P < 0.05)." (PMID 37192046, 2023). "The high expression of NCAPD2, NCAPG, NCAPH, NCAPD3, and NCAPH2 were all correlated with the relapse-free survival of sarcoma patients, HR = 2.76 (p = 3.3e-05), 2.72 (p = 0.0012), 2.71 (p = 0.0026), 1.87 (p = 0.01) and 2.08 (p = 0.029) respectively." (PMID 37192046, 2023). "In the Kaplan-Meier Plotter database, high expression of NCAPD2, NCAPG, NCAPH, and NCAPD3 was correlated with poor overall survival in sarcoma patients (p < 0.05), HR = 2.23 (p = 0.00016), 1.63 (p = 0.015), 1.83 (p = 0.0025), and 1.63 (p = 0.024), respectively." (PMID 37192046, 2023). "In this study, ONCOMINE, GEPIA, Kaplan-Meier plotter, DAVID (KEGG and GO analysis), and TIMER datasets were utilized to study the high expression, prognosis analysis, signal pathway and immune correlation of NCAPD2, NCAPG, NCAPH, NCAPD3, NCAPG2, and NCAPH2 in sarcoma for the first time." (PMID 37192046, 2023). "Up to now, NCAPD2, NCAPG, NCAPH, NCAPD3, NCAPG2, and NCAPH2 have not been mentioned in sarcoma, except NCAPG mentioned in Ewing sarcoma." (PMID 37192046, 2023).
breast tumor (1 paper, 2017). "Mcm6 and Ncapd2 are E2F targets as well, and little is known about their roles in breast tumor progression." (PMID 28212608, 2017).
colitis (1 paper, 2023). Inflammation of the colon. "Overexpression of NCAPD2 promotes the release of proinflammatory substances through the regulation of the IKK/NF-κB signaling pathway, which is also involved in the pathogenesis of colitis." (PMID 37498296, 2023).
fibrosarcoma (1 paper, 2023). A malignant mesenchymal fibroblastic neoplasm affecting the soft tissue and bone. "Firstly, in Detwiller Sarcoma dataset, NCAPD2 was overexpressed in Maligant Fibrous Histiocytoma, Fibrosarcoma and Leiomyosarcoma with 2.866 (p = 4.03E-6), 2.661 (p = 1.25E-4) and 2.690 (p = 0.002) fold changes." (PMID 37192046, 2023).
leiomyosarcoma (1 paper, 2023). An uncommon, aggressive malignant smooth muscle neoplasm, usually occurring in post-menopausal women. "In the Barretina Sarcoma dataset, NCAPD2 was overexpressed in Myxofibrosarcoma, Pleomorphic Liposarcoma, and Leiomyosarcoma with 2.627 (p = 4.43E-9), 2.118 (p = 1.21E-6) and 2.361 (p = 9.55E-8) fold changes." (PMID 37192046, 2023).
metastatic tumors (1 paper, 2025). "The results revealed that the control group exhibited higher expression levels of p-AKT, p-MDM2, and E2F1 in lung metastatic tumors compared to the NCAPD2 knockdown groups." (PMID 41319185, 2025).
urothelial carcinoma (1 paper, 2023). A malignant neoplasm derived from the transitional epithelium of the urinary tract (urinary bladder, ureter, urethra, or renal pelvis). "The TISIDB database showed that NCAPD2 expression was higher in responders than in nonresponders in urothelial carcinoma treated with the PD-L1 inhibitor atezolizumab." (PMID 37498296, 2023). "Through TISIDB, we found that NCAPD2 expression in responders was higher than that in nonresponders in urothelial carcinoma treated with the PD-L1 inhibitor, atezolizumab." (PMID 37498296, 2023).